VIM (vimentin)
Diseases named in the same sentence as VIM in open-access papers (continued):
Sharing a sentence is not in itself a finding about the gene and the disease.
tumor (continued). "DREH can bind to intermediate silk protein vimentin and inhibit its expression, thus inhibiting tumor metastasis of HBV-HCC." (PMID 34869051, 2021). "Double-knockdown of DNMT1 and DNMT3A, showed significantly higher miR-200c (a tumor suppressor in breast cancer) expression along with increased E-cadherin and decreased vimentin expression." (PMID 33572395, 2021). "High expression of vimentin, a mesenchymal-like cell-cell adhesion molecule, can lead to increasing invasiveness of tumor cells." (PMID 34045459, 2021). "Surface vimentin also has a role in human circulating tumor cells (CTCs), with CTCs being detected using a CSV antibody." (PMID 34299089, 2021). "During tumor progression, E-cadherin levels are downregulated and the levels of vimentin and α-SMA are upregulated." (PMID 33535182, 2021). "In the primary tumor samples, the level of E-cadherin expression was negatively associated with PRL-3 expression, and Vimentin has a positive correlation with PRL-3." (PMID 34147083, 2021). "We then examined the changes in the Vimentin and Twist protein levels in different groups in search of bio-factors related to tumor migration." (PMID 33707417, 2021). "The expression of the epithelial marker E-cadherin and the mesenchymal marker Vimentin was detected in tumor tissues." (PMID 33808696, 2021). "Vimentin expression was also increased in the tumor mass, whereas GFAP expression in the tumor mass was even slightly lower compared to its expression in the contralateral hemisphere." (PMID 34441246, 2021). "Immunohistochemically, this tumor tested positive for vimentin, CD 99, glypican-3, synaptopysin, WT-1, CK, and EMA." (PMID 34054966, 2021). "Giving that epithelial–mesenchymal transition (EMT) is activated during tumor invasion and metastasis, the immunofluorescence analysis of Vimentin (mesenchymal marker) was performed." (PMID 33838016, 2021). "EMT and vimentin expression play an important role in directed cell migration, which is a crucial step in tumor invasion." (PMID 33691719, 2021). "Immunohistochemical studies revealed that the tumor cells were positive for vimentin, synaptophysin, CD56, β-catenin, CD10, and progesterone receptor." (PMID 33650037, 2021). "In general, ezrin expression followed a similar pattern to vimentin throughout the passages, but with a more selective expression pattern according to the type of primary tumor." (PMID 34198671, 2021). "Ki-67, MMP-9, and vimentin are commonly used to evaluate the proliferative and invasive capacities of tumor cells, respectively, where increased expression indicates a higher capacity." (PMID 34635636, 2021). "Mice harboring bigenic tumors contained a greater number of circulating tumor cells and lung metastases as well as higher levels of activated Smad2, Akt, Erk, p38, Rac1 and more vimentin in the tumor tissues in situ than tumors expressing Neu alone." (PMID 33478130, 2021). "It is well known that E-cadherin, N-cadherin, and vimentin are key regulators of embryonic development, organ morphogenesis, and tumor growth, and are involved in epithelial cell motility via EMT." (PMID 34123785, 2021). "Studies have shown that vimentin is highly expressed in various tumor cells, especially in tumor cells with EMT." (PMID 34134721, 2021). "In particular, in RMS1, the upregulation of VIM in RT-PCR was consistent with the patient’s diagnosis in which the analyzed tumor specimen showed a diffuse positivity for vimentin with IHC and, more in general, with the mesenchymal origin of STS." (PMID 34768995, 2021). "Immunohistochemically, the tumor cells were diffusely positive for vimentin and focally positive for CD34 and alpha-SMA; lipoblasts were focally positive for S-100." (PMID 34797454, 2021). "We observed that the PRRX1-high tumours expressed several cancer-associated genes (e.g. MMP2/9, ZEB2, VIM)." (PMID 34496784, 2021).
tumor (continued). "Previous studies have shown that epithelial marker (E-cadherin) and mesenchymal markers (N-cadherin, vimentin) are crucial in tumor cell migration." (PMID 34830111, 2021). "Meanwhile, the risk of tumor metastasis was effectively inhibited by reducing the expression of tumor invasion-related signal molecules (TGF-β and vimentin) after combining treatment." (PMID 34794446, 2021). "On the immunohistochemical (IHC) study, the tumor cells were strongly positive for Melan A and Vimentin." (PMID 34307221, 2021). "RFA carried out at 50°C; for 2 min reduced HCC tissues only slightly but induced EMT of HCC cells in tumor tissues: increased expression of two mesenchymal markers (N-cadherin and vimentin) suppressed expression of an epithelial marker (E-cadherin)." (PMID 34900747, 2021). "Another class of Par-4 secretagogue, arylquins (AQ), can enhance Par-4 secretion by binding with vimentin, displacing Par-4 from vimentin for secretion, and efficiently inducing paracrine apoptosis of tumor cells." (PMID 33414404, 2021). "DREH can bind to intermediate filament protein vimentin and inhibit its expression, thus changing the normal cytoskeleton structure and inhibiting tumor metastasis." (PMID 34869051, 2021). "We found a weak positive correlation between PD-L1 and vimentin expressions in tumor cells (r = 0.25; p = 0.001)." (PMID 34917615, 2021). "The number of CTCs with CD45–EpCAM+CK7+Snail–N-cadherin+Vimentin+ phenotype had an inverse connection with grade and proliferative activity of the primary tumor." (PMID 33801519, 2021). "Vimentin, in various primary epithelial cancer cells and CTCs, is regarded as an accelerator for tumor progression and metastasis, and an independent marker for poor prognosis and survival." (PMID 34455700, 2021). "Both epithelial- and mesenchymal-associated genes were commonly expressed at higher levels in CTCs compared to the bulk primary tumour, although some common EMT-associated genes (CDH1, VIM, EGFR, EPCAM) remained unchanged." (PMID 34206049, 2021). "Vimentin is also expressed by epithelial-derived tumor cells, with expression higher in metastatic cancer cells than primary tumors." (PMID 34017688, 2021). "Due to its characteristics, vimentin has been considered as a predictive biomarker of tumor growth, poor tumor differentiation, and lymph node metastasis in HNSCCs." (PMID 34204259, 2021). "A prior study revealed the presence of reduced levels of LINC00675 in GC, playing a tumor suppressor role through the collapse of vimentin filaments." (PMID 34385891, 2021). "The tumor cells were strongly and diffusely positive in all cases for vimentin, S-100 protein, and HMB-45." (PMID 33340079, 2021). "Ascitic cells displayed a more elongated and polygonal shape than primary HGSOC tumour cells, showing lower expression of E-cad (green) and higher expression of VIM (red)." (PMID 34211089, 2021). "The IHC staining data showed that the jetPEI-delivered DCBLD2 siRNA efficiently inhibited DCBLD2 expression, which blocked EMT when mice were treated with cisplatin, leading to increased E-cadherin and decreased Vimentin expression in tumor tissues." (PMID 33808696, 2021). "Mice in this group showed similar tumor sizes and weights, and according expression level of epithelial–mesenchymal transition molecules, including vimentin, MMP9, MMP2, AXIN-1, N-cadherin, and E-cadherin, compared to mice in the control group." (PMID 33608495, 2021). "It was found that CFL1, N‐cadherin, and vimentin levels were reduced while E‐cadherin expression was increased in tumour tissues (CFL1 knockdown group) than in those from controlled tissues." (PMID 33784016, 2021). "Western blot analysis was employed to determine the expression of E-cadherin, Vimentin, Slug, Snail, and Twist in tumor tissues." (PMID 34001131, 2021). "IHC identified the protein expression levels of ANXA4 and the EMT signalling pathway factors E-cadherin, Vimentin and Snail in tumours." (PMID 33761465, 2021).
tumor (continued). "Vimentin expression was limited to tumour stromal cells, infiltrating inflammatory cells (lymphocytes and histiocytes) and blood vessels." (PMID 34809688, 2021). "The dual-colour IF staining also verified that the decreased E-cadherin expression but increased vimentin and fibronectin expression were observed in xenograft tumours derived from the anti-miR-199b-5p-transfected PCa cell model." (PMID 33239676, 2021). "Univariate analyses revealed that MACC1, E-cadherin, and vimentin levels along with T and N tumor classifications and cancer staging are significant prognostic factors of NPC (P<0.05)." (PMID 33854976, 2021). "VIM (vimentin) gene encodes type III intermediate filament protein and is expressed in most cell types, particularly tumor cells." (PMID 35047006, 2021). "We also costained luminal and claudin-low tumor sections for vimentin, E-cadherin, Arl13b, and γTubulin to assess EMT status and primary cilia representation." (PMID 34705506, 2021). "Clinically, many cancers display reduced E-cadherin and increased Vimentin expression that aids tumor progression and metastasis." (PMID 33500399, 2021). "The level of vimentin in tumor cells correlates well with increased tumor growth, invasion and poor prognosis." (PMID 34789743, 2021). "The differences between the two OS models are defined by the expression of tumour markers, vimentin and collagen." (PMID 34436447, 2021). "Nevertheless, our metastatic cells also showed enhanced levels of mesenchymal markers (i.e., N-cadherin and vimentin) in comparison with the tumour primary cell line." (PMID 33498690, 2021). "Our results showed that the TGF-β1/vimentin/focal adhesion protein assembly axis was involved in the control of the dynamics of initial tumor detachment under adequate nutrition, based on the Boyden chamber and 3D in-gel spheroid analysis." (PMID 34830801, 2021). "qRT‐PCR and Western blot assays were used to examine the expression levels of Piezo1, HIF‐1α, VEGF, vimentin and E‐cadherin in peritoneal metastatic GC tumour tissues." (PMID 33439514, 2021). "Vimentin contributes to cancer cell metastasis by maintaining heterotypic tumor cells during the collective invasion." (PMID 33801272, 2021). "DCBLD2 significantly reduced E-cadherin expression and increased Vimentin expression in tumor tissues in situ, as shown by IHC staining." (PMID 33808696, 2021). "RT-qPCR results showed SOX2OT silencing markedly changed the expression levels of E-cadherin, N-cadherin, and vimentin in the tumor tissues of nude mice." (PMID 33993197, 2021). "IHC staining confirmed lower expression of E-cadherin and higher expression of Vimentin in tumor tissues of mice treated with cisplatin compared to those of vehicle-treated mice." (PMID 33808696, 2021). "Surface vimentin has also been shown to have a role in other cancer cells, such as glioblastoma multiforme cancer stem cells, which are tumor-initiating cells that express vimentin on their surface." (PMID 34299089, 2021). "Immunohistological assays were applied to validate the expression of CXCL12, PDGFRA and VIM in normal and tumor tissues." (PMID 34801033, 2021). "Immunohistochemical staining showed that the tumor cells were positive for glial fibrillary acidic protein and vimentin." (PMID 34713831, 2021). "Western blot showed that E-cadherin was upregulated in shERp44 tumor sections, while Vimentin was downregulated." (PMID 33593371, 2021). "EMT is an important pathway for the invasion and metastasis of tumor cells, and hence, we detected the changes of the epithelial marker E-cadherin and the mesenchymal marker Vimentin." (PMID 34925506, 2021). "VIM was found to be expressed on the EVs from common OS cell lines such as HOS, 143B, MG63 and U2OS, and the upregulation of VIM in tumor sample was associated with the patients’ metastasis-free survival for 127 OS patients in R2 database." (PMID 34527582, 2021).
tumor (continued). "It is well documented that decreased PCNA and CCND1 expression is associated with retarded proliferation of tumor cells and that reduced MMP9 and Vimentin expression is closely related to slowed invasion of cancer cells." (PMID 34511432, 2021). "Immunohistochemically, tumor cells were positive for Vimentin (mesenchyme), CK7, CK19, MUC-1, MUC-5AC, MUC-6, S-100p (focal), Ki-67 (12%), and negative for Inhibin-α, ER, CK20, CEA, and MUC-2." (PMID 33592896, 2021). "As expected, clusters of VIM+ tumor cells were prevalent throughout cultures established in both Matrigel domes and fibrin/ccRCC ECM cultures." (PMID 34884982, 2021). "In this study, we retrospectively evaluated PD-L1 and vimentin expression in tumor cells, immune infiltrate and PD-L1 positive immune infiltrate via immunohistochemistry in tissue samples from resected non-metastatic NSCLC patients." (PMID 34917615, 2021). "Immunohistochemically, the tumor cells were positive for vimentin, smooth muscle actin (SMA), CD34, and epithelial membrane antigen (EMA); loss of the BAF47/INI1 protein in the tumor cells was also confirmed." (PMID 34193249, 2021). "Seventy-two HCC tumor samples were harvested for assessing the association of TOP2A expression with EMT in HCC cells through evaluation of TOP2A, E-cadherin, Snail, and vimentin levels." (PMID 34939898, 2021). "The presence of cells expressing αSMA, Vimentin, and S100A4 in the IMPC stroma suggested a role for tumor-associated fibroblasts in the IMPC microenvironment." (PMID 33761962, 2021). "While losing the original stroma of the tumor in successive passages, the vimentin staining was also lost." (PMID 34198671, 2021). "In both samples, E-Cadherin selectively identified the cancerous epithelial cells, Vimentin the tumor-associated fibroblasts, and CD3 the tumor-infiltrating T cells." (PMID 34620852, 2021). "In vivo experiment, knockdown of AKR1B10 promoted the growth of tumor, increased Vimentin, and E-cadherin significantly." (PMID 34552036, 2021). "In fibrin/ccRCC ECM cultures approximately 37% of cells are VIM+/CXCR4+ presumptive tumor cells, and 53% are VIM+/CXCR4− presumptive fibroblasts." (PMID 34884982, 2021). "The present study used dynamic-contrast enhanced MRI (DCE-MRI) to elucidate possible associations with tumor-infiltrating lymphocytes (TIL), stroma ratio and vimentin expression in head and neck squamous cell cancer (HNSCC)." (PMID 34801089, 2021). "IHC and TCGA analysis showed that the expression of PKD3, the frequency and intensity of PDK3 nuclear staining, and the expression of Vimentin gradually increased with advanced tumour grade." (PMID 33692335, 2021). "Immunohistostaining studies revealed that the tumor cells were positive for vimentin, synaptophysin, cluster of differentiation (CD) 56, β-catenin, CD10, and progesterone receptor." (PMID 33650037, 2021). "During the EMT process, decrease of E-cadherin and increase of vimentin includes cellular mobility and invasion of tumor cells." (PMID 33632213, 2021). "Currently, there are aptamers against vimentin for isolation of circulating tumor cells undergoing epithelial mesenchymal transition." (PMID 34770931, 2021). "The expression of ADAM10, Notch1, Notch2, Notch3, Notch4, Hey1, vimentin and N‐cadherin at the transcript level was significantly upregulated, whereas transcripts of E‐cadherin significantly decreased in tumour tissues versus in normal liver tissues of HCC." (PMID 33955149, 2021). "EMT can increase migration and invasion potential of tumor cells by increasing expression of mesenchymal biomarkers, N-cadherin, vimentin and fibronectin and decreasing epithelial cell phenotype biomarkers like E-cadherin." (PMID 33614637, 2021).
tumor (continued). "On the other hand, the number of cells expressing cytoplasmic vimentin in the invasive front of the tumor was significantly (p = 0.0494) higher compared to that in normal mucosa." (PMID 34638929, 2021). "We investigated the cellular properties by combined staining for CK8/18 and vimentin and noticed that the majority of cells inside the tumor mass expressed CK8/18." (PMID 34290694, 2021). "Our findings, together with the published data indicate that vimentin plays an important role in different cellular processes responsible of tumour development and disease relapse." (PMID 34203746, 2021). "This coincides with the fact that the vimentin-expressing cells in their corresponding primary tumor were mostly stromal cells." (PMID 34198671, 2021). "The prognostic risk score was an independent risk factor for the prognosis of GC, which was significantly correlated with N stage and tumor location, positively correlated with the VIM gene, and negatively correlated with the CDH1 gene." (PMID 34745226, 2021). "Our results showed that the expression levels of CBX7 and E-cad in the CC tissues were lower than those in the adjacent non-tumorous tissues, whereas the expression level of VIM was higher." (PMID 33748425, 2021). "The expression of N-cadherin and vimentin, that are markers of mesenchymal cells, was upregulated in tumor and PVTT tissues." (PMID 34504839, 2021). "At diagnosis, the tumor contained a dominant sarcomatous component positive for vimentin and a focal carcinomatous component positive for E-cadherin." (PMID 34257602, 2021). "Tumor-bearing mice treated with cisplatin showed decreased level of E-cadherin and elevated level of Vimentin, while nude mice inoculated with shDCBLD2 cells showed a reduction in cisplatin-induced EMT." (PMID 33808696, 2021). "We found that positive miR-106b-5p expression was significantly correlated with low levels of TET1 in tumour specimens, with the tumour specimens positive for miR-106b-5p usually presenting low E-cadherin and high Vimentin expression." (PMID 33985545, 2021). "Certain EMT phenotypes such as impaired E-cadherin expression or aberrant induction of Vimentin and N-cadherin are related with enhanced tumor metastasis." (PMID 32879302, 2020). "More importantly, the role of KLF7 in driving EMT by regulating Vimentin levels, was also confirmed in the spheroid models, these latter more closely resembling the in vivo tumour growth situation." (PMID 33250051, 2020). "Immunohistochemical analysis can be helpful, and the tumor is often positive for smooth muscle actin, vimentin, and desmin." (PMID 31641928, 2020). "In one study performed on colon cancer, the GRP78-activated NRF-2/HO-1 signaling pathway was suggested to promote EMT with decreased E-cadherin and increased vimentin expression in the tumor cells." (PMID 32268506, 2020). "Vimentin and Twist1 positivity was observed in close proximity to necrotic areas in early passages and less commonly found at the centre of tumour ‘islands’." (PMID 33276802, 2020). "We confirmed that overexpression of miR-146a significantly suppresses cell proliferation, colony and tumor formation, as well as migration and invasion through inhibition of vimentin." (PMID 33248456, 2020). "The perineural and intraneural invasion of CK7- and vimentin-positive tumor cells was detected, as well as the presence of tumor cells inside the blood vessels." (PMID 32093026, 2020). "Two of the clusters have high expression of genes related to mesenchymal phenotype (e.g., CDH2, SNAI2, ZEB1, TWIST1, and VIM) which were assigned as tumor cells with EMT characteristics (EMT+)." (PMID 32988401, 2020). "We found that vimentin expression was significantly upregulated, while E-cadherin expression was downregulated in the co-transplantation tumor tissues (p < 0.001)." (PMID 33372604, 2020). "Immunohistochemically, the tumour cells were positive for vimentin, α-smooth muscle actin, and desmin." (PMID 32787426, 2020).